RNU6ATAC7P (RNA, U6atac small nuclear 7, pseudogene)
Gene: Small nuclear RNA gene on chromosome 17 (31,563,768 to 31,563,894, reverse strand). Ensembl gene ENSG00000221038.
Homologues: Orthologues: chimpanzee RNU6ATAC7P (100% identical), macaque RNU6ATAC7P (87% identical). Paralogues in human: RNU6ATAC (88% identical), RNU6ATAC21P (83% identical), RNU6ATAC27P (81% identical), RNU6ATAC6P (80% identical), RNU6ATAC8P (80% identical), RNU6ATAC41P (77% identical), RNU6ATAC19P (62% identical), RNU6ATAC39P (57% identical), RNU6ATAC22P (54% identical).